CHGA (chromogranin A)
Diseases named in the same sentence as CHGA in open-access papers (continued):
Sharing a sentence is not in itself a finding about the gene and the disease.
rectal cancer (4 papers, 2022 to 2025). A primary or metastatic malignant neoplasm that affects the rectum. "Copy number variations of core hub genes are widely present in colon and rectal cancers, with CHGA and FANCD2 primarily showing copy number heterozygous deletion, while the rest mainly exhibit copy number heterozygous amplification." (PMID 39120548, 2024). "Further, the diagnosis and prognosis value of CHGA in both colon and rectal cancer were evaluated, which indicated that CHGA could be a promising diagnostic biomarker but not a prognostic biomarker in CRC." (PMID 35681650, 2022).
renal failure (4 papers, 1998 to 2021). "Since chromogranin A levels are markedly increased in renal failure, it seems very unlikely that decreased CBF levels are the consequence of decreased precursors." (PMID 34647168, 2021). "NSE (Cispack NSE, Cis Bio International, Gif-sur-Yvette, France; normal <12.5 microg l(-1)), and chromogranin A (CgA-Riact, Cis Bio International, normal <100 microg l(-1)) were measured in 128 patients without renal insufficiency." (PMID 9792158, 1998).
schizophrenia (4 papers, 2012 to 2021). A major psychotic disorder characterized by abnormalities in the perception or expression of reality. "We have also demonstrated that the levels of hormones such as insulin, cortisol, progestone, prolactin, growth hormone and chromogranin A are altered in the circulation of first onset schizophrenia patients compared to controls." (PMID 23118852, 2012). "This confirmed that interferon-γ (p = 0.043, FC = 1.4) and chromogranin A (p = 0.004, FC = −1.3) were present at significantly different levels between schizophrenia and control samples." (PMID 23118852, 2012). "This showed that 9 of the analytes (C-reactive protein, cortisol, resistin, TIMP-1, chromogranin A, VEGF, thrombopoetin, alpha-2 macroglobulin, and glutathione S-transferase) were also found to be reproducibly altered between schizophrenia and control subjects in serum." (PMID 23118852, 2012).
acute coronary syndrome (3 papers, 2012 to 2022). Signs and symptoms related to acute ischemia of the myocardium secondary to coronary artery disease. "In recent years, CHGA has been found to be a sensitive marker of prognosis of morbidity and mortality in acute coronary syndromes (ACS), the mechanism for the predictive effects could probably contribute to the downstream product catestatin." (PMID 25848973, 2015).
adrenocortical neoplasms (3 papers, 2014 to 2024). "The accessible sources all state consistently that chromogranin A immunoreactivity is negative in all cases of adrenocortical tumours." (PMID 24602387, 2014). "Concerning the specificity of STX1, many endocrine tumors known to express either CHGA or SYP, such as parathyroid and adrenocortical neoplasms, were consistently negative for STX1." (PMID 32059362, 2020).
atherosclerosis (3 papers, 2012 to 2021). A disease characterized by the build-up of fatty material and calcium deposition in the arterial wall resulting in partial or complete occlusion of the arterial lumen. "The biological role of CHGA in the pathogenesis of atherosclerosis is not known but the ∼6-fold up-regulation specifically in aortic plaques may inspire future research." (PMID 22509262, 2012).
breast tumors (3 papers, 2010 to 2022). "Discussion: Syntaxin-1 and INSM1 are sensitive and specific markers of breast tumors with neuroendocrine features, outperforming chromogranin A and CD56." (PMID 34764822, 2021). "Sensitivity and specificity of currently used markers are limited; based on the definitions of WHO Classification of Tumours, 5th edition, about 50% of breast tumors with features of neuroendocrine differentiation express chromogranin-A and 16% express synaptophysin." (PMID 34764822, 2021). "We isolated human breast tumors that displayed NED based on their co‐expression of four NED markers SCG2, CHGB, CHGA, and synaptophysin, SYP." (PMID 35653631, 2022).
COVID-19 (3 papers, 2022 to 2023). A disease caused by infection with severe acute respiratory syndrome coronavirus 2. "The aim of this study was to analyze salivary mental stress biomarkers as cortisol, alpha-amylase, and chromogranin A in hospitalized patients with COVID-19 to compare their potential relationship with stress symptoms." (PMID 36405600, 2022).
gastric adenocarcinoma (3 papers, 2022 to 2026). "Western blotting also showed high expression of SPINK4, TTR, PCSK1N, CHGA and GHRL in gastric adenocarcinoma cell lines, with GHRL showing the most significant increase (p < 0.05)." (PMID 38752750, 2024). "Immunohistochemical analysis showed that these cells expressed cytokeratin 7 but not cytokeratin 20, CD117, CD34, chromogranin A, and synaptophysin, confirming the diagnosis of exophytic gastric adenocarcinoma with peritoneal dissemination." (PMID 42017098, 2026).
gastrointestinal stromal tumor (3 papers, 2016 to 2025). "Gastrointestinal stromal tumor, smooth muscle tumor, and adenocarcinoma can easily be excluded with immunohistochemical staining for S100 protein, synaptophysin, and/or chromogranin A. Ganglioneuroma lacks the epithelioid component, while GP usually shows a prominent epithelioid component." (PMID 28096810, 2016). "Miscellaneous indications, each accounting for a single participant, were elevated chromogranin A levels, and surveillance following gastrointestinal stromal tumor (GIST) treatment." (PMID 40740298, 2025). "In the majority of cases, schwannoma, gastrointestinal stromal tumor, and leiomyoma can be easily distinguished using immunohistochemical staining (S-100 protein, c-Kit, CD34, synaptophysin, and chromogranin A)." (PMID 30101131, 2018).
ovarian carcinoma (3 papers, 2020 to 2024). A malignant neoplasm originating from the surface ovarian epithelium. "This neuronal or epithelial signature of ovarian carcinomas is raised from a rare cell type found in regular (non-tumoral) ovarian tissues which have a particular phenotype expressing Tyrosine hydroxylase, ChgA, the paraneoplastic protein PNMA1 and KRT80." (PMID 39592661, 2024).
parathyroid carcinoma (3 papers, 2009 to 2021). "Higher expression of chromogranin A (CgA) further confirmed parathyroid carcinoma as a rare endocrine tumor." (PMID 30290620, 2018). "A right emithyroidectomy and right superior and inferior parathyroidectomy was performed and histopathological examination showed a parathyroid carcinoma (immunohistochemistry positive for PTH and chromogranin A, Ki-67 10%) associated with follicular hyperplasia." (PMID 22276015, 2009).
Parkinson disease (3 papers, 2020 to 2021). A progressive degenerative disorder of the central nervous system characterized by loss of dopamine producing neurons in the substantia nigra and the presence of Lewy bodies in the substantia nigra and locus coeruleus. "In addition to AD, CHGA also accumulates in brain areas with neuronal degeneration in Parkinson ́s and Pick ́s disease, suggesting that this protein could be a useful biomarker for various neurological disorders." (PMID 32370154, 2020).
periodontitis (3 papers, 2015 to 2024). An acute or chronic inflammatory process that affects the tissues that surround and support the teeth. "Our data on salivary biomarkers, namely salivary cortisol and chromogranin A levels and cortisol/DHEA ratio, can assist researchers and clinicians in overcoming the difficulties in the diagnosis of periodontitis, thereby increasing diagnostic accuracy." (PMID 37113482, 2023). "Factors predicting above-average chromogranin A values were periodontitis in healthy controls (OR = 16.235; p < 0.001) and periodontitis and gingivitis (OR = 3.080; p = 0.033)." (PMID 37113482, 2023). "Other researchers found significantly higher chromogranin A levels in the saliva samples of patients with aggressive periodontitis than in those of patients with chronic periodontitis and healthy controls." (PMID 37113482, 2023). "Regarding the cortisol and chromogranin A levels, differences were observed even between the two periodontal disease groups (i.e., gingivitis and periodontitis groups)." (PMID 37113482, 2023). "Meanwhile, our study was the first, to the best of our knowledge, to simultaneously measure cortisol and chromogranin A levels in patients with periodontitis." (PMID 37113482, 2023). "Additionally, salivary cortisol and chromogranin A levels were more significant biomarker predictors for periodontitis and the severity of periodontal diseases." (PMID 37113482, 2023). "Furthermore, we studied the correlations among cortisol, DHEA, and chromogranin A levels and attempted to identify potent biomarker predictors of psychological stress in patients with gingivitis and periodontitis in comparison with those in healthy controls." (PMID 37113482, 2023). "In summary, this was the first study to simultaneously assess the cortisol level, DHEA, cortisol/DHEA ratio, and chromogranin A level in patients with periodontal diseases, comprising gingivitis and periodontitis, and compare the values of these markers with those of healthy controls." (PMID 37113482, 2023). "Therefore, the stress-related neuroendocrine factors of cortisol, DHEA, cortisol/DHEA ratio, and chromogranin A were higher among patients with gingivitis and periodontitis than in healthy controls." (PMID 37113482, 2023). "Therefore, numerous evidences suggest that chromogranin A is a potential novel biomarker of periodontitis." (PMID 37113482, 2023). "Furthermore, the DHEA, cortisol/DHEA ratio, cortisol, and chromogranin A values were more significant predictors of periodontitis than of healthy controls." (PMID 37113482, 2023). "Therefore, the direct measurement of psychological stress through salivary cortisol, DHEA, and chromogranin A levels is required in patients with periodontal diseases, such as gingivitis and periodontitis." (PMID 37113482, 2023). "The salivary chromogranin A level was significantly higher in the gingivitis group (204.71 ± 34.20 ng/mL) than in the healthy control group (127.17 ± 46.68 ng/mL), and significantly higher in the periodontitis group (245.90 ± 69.31 ng/mL) than in the gingivitis group (p < 0.001)." (PMID 37113482, 2023). "Salivary cortisol and chromogranin A levels increased with the severity of periodontal disease; their levels were the highest in the periodontitis group and were significantly higher in the following descending order: periodontitis, gingivitis, and healthy control groups (all values of p < 0.001)." (PMID 37113482, 2023). "The relationship between periodontitis and psycho-neuro-immunological parameters, such as psychological stress, cortisol, dehydroepiandrosterone (DHEA), and chromogranin A, has rarely been studied." (PMID 37113482, 2023). "In our study, chromogranin A levels significantly increased in the following order: healthy controls followed by patients with gingivitis and periodontitis; however, they were not a significant predictor of psychological stress in patients with periodontitis." (PMID 37113482, 2023).
periodontitis (continued). "Thus, our results suggest that chromogranin A could be a biomarker of gingivitis and periodontitis, although not biomarker of psychological stress in such patients." (PMID 37113482, 2023).
pituitary adenomas (3 papers, 2016 to 2025). "The lesions were also negative for chromogranin A, a neuroendocrine granule marker often expressed in clinically non-functioning pituitary adenomas." (PMID 30912742, 2019).
preeclampsia (3 papers, 2021 to 2024). Preeclampsia is a hypertensive disorder of pregnancy that is characterized by new-onset hypertension with proteinuria presenting after 20 weeks of gestation, and depending on mild or severe forms may initially present with severe headache, visual disturbances, and hyperreflexia. "This study for the first time reveals that chromogranin A gene expression level is associated with preeclampsia." (PMID 34620125, 2021). "The further studies are necessary to examine the association between hormonal status and chromogranin A action in the context of preeclampsia." (PMID 34620125, 2021). "This suggests that chromogranin A may be implicated in the fetal-sex-specific pathomechanism of preeclampsia." (PMID 34620125, 2021). "This suggests that patomechanism of preeclampsia may differ between pregnancies bearing male and female foetuses and chromogranin A, and its derived peptide might be implicated in the patomechanism of preeclampsia induced by female foetus." (PMID 34620125, 2021). "Therefore, the main aim of the proposed study is to determine whether chromogranin A is related with the occurrence of preeclampsia." (PMID 34620125, 2021). "Apart from the two stimulation variants reflecting a preeclampsia-like environment (PLE1: 2%O2 + 1 ng/mL IL6 + 10 μM H2O2 and PLE2: 2%O2 + 10 ng/mL IL6 + 50 μM H2O2), no significant changes in CHGA gene expression were obtained in the HTR-8/SVneo and BeWO cell lines compared to controls." (PMID 37108287, 2023).
rhabdomyosarcoma (3 papers, 2019 to 2025). A rare aggressive malignant mesenchymal neoplasm arising from skeletal muscle. "Immunohistochemistry showed positivity for rhabdomyosarcoma markers such as Desmin, MyoD1, and Myogenin in the rhabdomyosarcomatous component and positivity for neuroectodermal markers, including synaptophysin and chromogranin A in the neuroectodermal component." (PMID 41465905, 2025).
type 2 diabetes (3 papers, 2025 to 2026). "Chromogranin A (CgA) is a pro-hormone widely expressed in neuroendocrine tissues and elevated in both type 1 (T1D) and type 2 diabetes (T2D)." (PMID 42051247, 2026). "Tissue biopsies from 36 adult donor pancreases with/without type 2 diabetes were collected from 16 anatomically defined regions, with H&E, Sirius Red Fast Green and chromogranin A immunohistochemical staining and quantification performed." (PMID 40991018, 2025).
adenocarcinoma of the lung (2 papers, 2016 to 2023). "A biopsy from the lesion revealed an adenocarcinoma of the lung (TTF1-positive, negative for markers of neuroendocrine differentiation such as chromogranin A and synaptophysin 38)." (PMID 27776522, 2016).
amyotrophic lateral sclerosis (2 papers, 2011 to 2020). Amyotrophic lateral sclerosis (ALS) is a neurodegenerative disease characterized by progressive muscular paralysis reflecting degeneration of motor neurons in the primary motor cortex, corticospinal tracts, brainstem and spinal cord. "In fact, the potential of CHGA as biomarker in CSF has been investigated in prion-like neurodegenerative diseases such as AD or amyotrophic lateral sclerosis." (PMID 32370154, 2020). "Chromogranin A was recently discovered to bind to mutant superoxid dismutase activity in amyotrophic lateral sclerosis increasing neurotoxicity." (PMID 22046305, 2011).
asthma (2 papers, 2018 to 2021). "Elshafie and colleagues also reported that increased wheezing in a patient with asthma was associated with increased serum levels of chromogranin A." (PMID 30081920, 2018). "One patient (pt.2) had a mildly elevated chromogranin A (CgA) level of 111 ng/mL (normal 0–95 ng/mL), but also suffered from asthma and took a serotonin specific reuptake inhibitor, which are both factors that can lead to an elevation of CgA." (PMID 33377995, 2021). "One study reported increased serum levels of chromogranin A in a mixed population of individuals, some of which had asthma." (PMID 30081920, 2018).
autoimmune disease (2 papers, 2022 to 2024). A disorder resulting from loss of function or tissue destruction of an organ or multiple organs, arising from humoral or cellular immune responses of the individual to their own tissue constituents. "This notion is supported by recent reports suggesting that CHGA may serve as a biomarker for some autoimmune diseases including T1D6,7." (PMID 35241690, 2022).
autoimmune gastritis (2 papers, 2023 to 2024). Inflammation of the body fundic mucosa of the stomach. "However, chromogranin A can be elevated in multiple conditions, and it is not recommended as a diagnostic test for autoimmune gastritis." (PMID 38610988, 2024).
celiac disease (2 papers, 2021 to 2023). An autoimmune genetic disorder with an unknown pattern of inheritance that primarily affects the digestive tract. "By contrast, ghrelin from X/A-like cells and other chromogranin A (CHGA)+ cells increase in the duodenum of celiac disease patients and correlate with inflammation." (PMID 37240181, 2023). "In this study, we found that two serum markers, namely chromogranin A and β2-microglobuline, can predict these complications in patients with coeliac disease." (PMID 34064688, 2021).
chronic pancreatitis (2 papers, 2020 to 2021). A chronic inflammatory process causing damage and fibrosis of the pancreatic parenchyma. "In early chronic pancreatitis, pancreatic fibrosis is dominant in the head location, and duodenum mucosa chromogranin-A is a potential biomarker with increased expression in an age-matched manner." (PMID 34359334, 2021). "The early chronic pancreatitis group showed higher expression of duodenal mucosa chromogranin-A." (PMID 34359334, 2021).
colorectal adenocarcinoma (2 papers, 2012 to 2014). The most common type of colorectal carcinoma. "Usually, GCCs stain scattered positively for the neuroendocrine markers chromogranin A and synaptophysin but similar to the present case, they also produce mucin like colorectal adenocarcinomas." (PMID 23304574, 2012). "The colorectal adenocarcinomas did not express the neuroendocrine cell marker chromogranin-A (data not shown)." (PMID 24915894, 2014).
colorectal tumors (2 papers, 2016 to 2020). "Whilst chromogranin A-positive enteroendocrine cells are also Brachyury-positive in colorectal tumours, expression of Brachyury becomes more diffuse in these samples, suggesting a more widespread function in cancer." (PMID 26862851, 2016).
ductal adenocarcinoma (2 papers, 2017 to 2018). "According to immunohistochemistry performed on paraffin blocks in France, infiltrating ductal carcinoma with a strong neuroendocrine component was confirmed by CD56, CD57, and chromogranin A markers." (PMID 29082059, 2017).
dyspepsia (2 papers, 2021 to 2026). An uncomfortable, often painful feeling in the stomach, resulting from impaired digestion. "Delayed gastric emptying was more common in functional dyspepsia and chromogranin-A was expressed more in pancreatic fibrosis." (PMID 34359334, 2021). "Between pancreatic fibrosis and functional dyspepsia in the present case series, duodenal mucosa chromogranin-A, a surrogate of enteroendocrine cells, had significantly higher expression in the pancreatic fibrosis group by age-matched comparison, but not cholecystokinin or glucagon-like peptide-1." (PMID 34359334, 2021). "This case presents a 69-year-old female who presented with dyspepsia, and on subsequent endoscopic evaluation, she was found to have AMAG in the context of elevated levels of serum chromogranin A (CgA) and gastrin, suggestive of a GNET." (PMID 41728546, 2026).
goblet-cell adenocarcinoma (2 papers, 2008 to 2024). "It is known that tubular carcinoid is stained weakly for chromogranin A, while goblet cell carcinoids are stained more intensively for the same substance." (PMID 18252007, 2008). "Based on our results we find out that apart from the described serotonin-, somatostatin- and chromogranin A-positive endocrine cells, the goblet cell carcinoid contains also synaptophysin-positive endocrine cells." (PMID 18252007, 2008). "Immunohistochemical testing was performed using synaptophysin, chromogranin A, neuronal specific enolase, CD56, CDX-2, CK20, CEA, MUC2 and Ki67, thus establishing the final diagnosis of high-grade extra-appendiceal goblet-cell adenocarcinoma of the cecum, G3." (PMID 40729214, 2024).